ABCG8 (ATP binding cassette subfamily G member 8)
Description:
ABCG5 and ABCG8 form an obligate heterodimer that mediates Mg(2+)- and ATP-dependent sterol transport across the cell membrane. Plays an essential role in the selective transport of the dietary cholesterol in and out of the enterocytes and in the selective sterol excretion by the liver into bile. Required for normal sterol homeostasis. The heterodimer with ABCG5 has ATPase activity.
Synonyms: GBD4; STSL; STSL1
Tractability: Small molecule: a structure with a bound ligand is known. Antibody: UniProt places it where antibodies can reach, with high confidence; its Gene Ontology location is reachable by antibodies, with high confidence; UniProt predicts a signal peptide or a membrane-spanning region. PROTAC: its protein half-life has been measured.
Gene: Protein-coding gene on chromosome 2 (43,831,942 to 43,882,988, forward strand). Ensembl gene ENSG00000143921.
Subcellular location: Cell membrane; Apical cell membrane
Subcellular location (Human Protein Atlas): Vesicles
Pathways (Reactome):
Disease: Defective ABCG5 causes sitosterolemia; Defective ABCG8 causes GBD4 and sitosterolemia
Signal Transduction: NR1H3 & NR1H2 regulate gene expression linked to cholesterol transport and efflux
Transport of small molecules: ABC transporters in lipid homeostasis
Gene Ontology:
Molecular function: ATP binding; ATP hydrolysis activity; ATPase-coupled transmembrane transporter activity; cholesterol transfer activity; protein binding; protein heterodimerization activity; ABC-type transporter activity; protein dimerization activity
Biological process: cholesterol efflux; cholesterol homeostasis; negative regulation of intestinal cholesterol absorption; negative regulation of intestinal phytosterol absorption; intestinal cholesterol absorption; sterol transport; lipid transport; response to muscle activity; response to nutrient; response to nutrient levels; response to xenobiotic stimulus; transmembrane transport; triglyceride homeostasis
Cellular component: apical plasma membrane; ATP-binding cassette (ABC) transporter complex; receptor complex; plasma membrane; membrane
Genetic constraint (gnomAD): Loss-of-function variants: 82 observed, 74.13 expected, observed/expected ratio (o/e) 1.11, 90% interval 0.92 to 1.33. The synonymous counts are far from expectation, so gnomAD's model fits this gene poorly and the ratio says little. Missense variants: 1,119 observed, 904.13 expected, observed/expected ratio (o/e) 1.24, 90% interval 1.18 to 1.3. Synonymous variants: 451 observed, 370.42 expected, observed/expected ratio (o/e) 1.22, 90% interval 1.13 to 1.32.
Gene-disease validity (ClinGen):
ClinGen rates the evidence that ABCG8 causes each of these diseases.
sitosterolemia (autosomal recessive): Definitive. A rare autosomal recessive sterol storage disease characterized by the accumulation of phytosterols in the blood and tissues.
Homologues: Orthologues: chimpanzee ABCG8 (99% identical), macaque ABCG8 (93% identical), rabbit ABCG8 (84% identical), dog ABCG8 (82% identical), mouse Abcg8 (82% identical), rat Abcg8 (80% identical), guinea pig ABCG8 (78% identical), pig ABCG8 (76% identical), zebrafish abcg8 (31% identical), Drosophila melanogaster w (25% identical), Caenorhabditis elegans wht-1 (24% identical), Drosophila melanogaster st (24% identical), and 8 more. Paralogues in human: ABCG2 (27% identical), ABCG5 (24% identical), ABCG4 (22% identical), ABCG1 (22% identical).
Diseases named in the same sentence as ABCG8 in open-access papers:
ABCG8 is named in the same sentence as 80 diseases in open-access papers, as found by Europe PMC text mining. Sharing a sentence is not in itself a finding about the gene and the disease. The quoted sentences say what the papers report.
sitosterolemia (65 papers, 2004 to 2026). "Sitosterolemia is a rare autosomal recessive lipid metabolic disorder caused by mutations in ABCG5 or ABCG8, leading to pathological accumulation of dietary plant sterols." (PMID 42111500, 2026). "Fourteen variants were detected, nine in ABCG5 and five in ABCG8, with five variants reported for the first time in sitosterolemia patients." (PMID 39860331, 2025). "Mutations in ABCG5 or ABCG8 lead to increased intestinal absorption and decreased biliary excretion of plant sterols and cholesterol, resulting in sitosterolemia." (PMID 39860331, 2025). "After a multidisciplinary discussion in 2018, genomic DNA was extracted in order tosequence CYP27A1 and ABCG8 genes, associated withCTX and sitosterolemia, respectively." (PMID 40532043, 2025). "In our study, the diagnosis of sitosterolemia in 14 patients was confirmed based on the presence of disease-causing variants in the ABCG5 or ABCG8 genes, along with elevated levels of TC and LDL-C." (PMID 39860331, 2025). "The second was a canonical splice acceptor variant in ABCG8 (NM_022437.2:c.965-1G>C; rs957176669), reported as pathogenic in ClinVar and associated with sitosterolemia." (PMID 41170196, 2025). "Three variants, ABCG5: c.1573C>T and ABCG8: c.687G>A and c.1757-2A>G, were previously identified by Invitae in sitosterolemia patients who were part of this study." (PMID 39860331, 2025). "Phytosterolemia is a rare AR disorder caused by biallelic ABCG5 or ABCG8 mutations, leading to phytosterol accumulation." (PMID 40941697, 2025). "Treatment is different for people with sitosterolemia due to ABCG5/ABCG8 pathogenic variants that cause severe hypercholesterolemia and ASCVD and can phenocopy FH." (PMID 40004987, 2025). "The molecular pathogenesis of sitosterolemia results from biallelic mutations affecting the ABCG5 or ABCG8 genes, these two genes encode ATP-binding cassette transporters critical for regulating intestinal absorption and biliary excretion of plant sterols." (PMID 41170196, 2025). "Type 2 sitosterolemia (ABCG5) or type 1 sitosterolemia (ABCG8) gene variations are the cause of sitosterolemia, and the ABCG5 and ABCG8 transporter proteins are highly expressed in the human liver and small intestine." (PMID 38509578, 2024). "It is estimated that at least 1 in 200,000 people in the general population have sitosterolemia caused by pathogenic variants in ABCG5 or ABCG8." (PMID 38540356, 2024). "A genetic study can be conducted to analyze DNA mutations in the ABCG5 or ABCG8 gene and confirm the diagnosis of sitosterolemia." (PMID 39055399, 2024). "Sitosterolemia is considered an extremely rare recessive disorder caused by pathogenic variants in ABCG5 or ABCG8 in both alleles." (PMID 38540356, 2024). "Almost all ABCG5/ABCG8 loss-of-function variants identified in our cohort have been reported before in patients with sitosterolemia providing evidence to be classified as pathogenic or likely pathogenic." (PMID 38122934, 2023). "By contrast, mutations in ABCG8 were more commonly encountered in Caucasian populations with sitosterolemia." (PMID 36981027, 2023). "Four control subjects were heterozygous for a pathogenic variant in ABCG8 (NM_022437.3; c.1720G > A; p.Gly574Arg), indicating carrier status for recessively inherited sitosterolemia." (PMID 35300601, 2022). "An observation from inherited disease patients with ABCG5 and/or ABCG8 deficiency presented sitosterolemia and premature coronary disease." (PMID 33801029, 2021). "One of the ALT-increasing allele is a coding ABCG8 variant previously associated with the Mendelian disease sitosterolemia." (PMID 33547301, 2021). "Frameshift mutations in exon 13 of both ABCG5 and ABCG8 cause sitosterolemia, indicating little tolerance for truncation of the protein." (PMID 33807969, 2021).
sitosterolemia (continued). "Deficiency of ABCG5 or ABCG8 in sitosterolemia impairs excretion of plant sterol into the intestinal lumen from enterocytes and into bile in the liver, thereby resulting in a severe accumulation of plant sterols in plasma and tissues." (PMID 35096999, 2021). "Next-generation sequencing was later performed, which revealed a nonsense mutation in the ABCG8 gene, which led to the diagnosis of sitosterolemia." (PMID 35096999, 2021). "Mutations in human ABCG5 or ABCG8 cause sitosterolemia, a disease characterized by increased absorption and decreased biliary excretion of dietary phytosterols such as the common plant sterol β-sitosterol." (PMID 33575564, 2020). "ABCG5 or ABCG8 gene have been shown to be associated with LDL cholesterol level through common genetic variations as well as rare variations leading to sitosterolemia, a recessive Mendelian disorder." (PMID 31901240, 2020). "Sitosterolemia is an extremely rare autosomal recessive disease caused by mutations in either ABCG5 or ABCG8, which encode for a sterol efflux transporter (sterolin) that pumps sterols out into the intestinal lumen or into bile." (PMID 33204594, 2020). "Here, we report a case of sitosterolemia caused by a novel nonsense variant and an East Asian population-specific missense variant in the ABCG8 gene in a compound heterozygous state." (PMID 33014402, 2020). "Researchers including ourselves have shown the great effectiveness of ezetimibe in the case of sitosterolemia who has double mutations in ATP-binding cassette sub-family G member 5 or 8 (ABCG5) or (ABCG8) gene." (PMID 31901240, 2020). "Inactivation of either ABCG5 or ABCG8 causes sitosterolemia, a genetic disorder characterized by sterol accumulation and premature coronary atherosclerosis." (PMID 30679232, 2019). "Genetic variation in ABCG5 and ABCG8 has been associated with sitosterolemia while GWAS has recently implicated SORT1 as a novel locus for LDL cholesterol." (PMID 24503134, 2014). "Mutations in ABCG5 or ABCG8, comprising the sitosterolemia locus, STSL, are now known to cause this disease." (PMID 16026620, 2005). "Note that patients with sitosterolemia, mutated in Abcg8, have been reported to manifest hyper-absorption of cholesterol, as well as plant sterols." (PMID 16026620, 2005). "In conclusion, we described a case of sitosterolemia with a homozygous mutation inthe ABCG8 gene." (PMID 40532043, 2025). "Notably, five variants, including ABCG5: c.403-2A>T and c.1573C>T, and ABCG8: c.382A>T, c.687G>A, and c.1757-2A>G, were documented for the first time in sitosterolemia patients." (PMID 39860331, 2025). "Sitosterolemia is a rare genetic lipid disorder caused by mutations in theABCG5/ABCG8, genes." (PMID 40532043, 2025). "Mutations in the ABCG5 and ABCG8 genes are associated with pathological changes in sitosterolemia." (PMID 36937651, 2023). "Mutations in different genes have been shown to cause monogenic dyslipidemia, including LDLRAP1 mutations that are involved in autosomal recessive hypercholesterolemia, ABCG5/ABCG8, involved in sitosterolemia, or LMF1, which is associated with familial chylomicronemia syndrome." (PMID 37887310, 2023). "Mutations in the ABCG8 gene have been reported to be associated with the rare autosomal recessive lipid metabolic disorder Sitosterolemia, recently linked to four cases of hemolytic anemia with signs such as stomatocytic hemolysis, macrothrombocytopenia, and splenomegaly." (PMID 35572556, 2022). "Nonetheless, this classification system provides a framework for characterizing ABCG5 ABCG8 mutants that cause sitosterolemia and a basis for the systematic investigation of compounds that may potentially rescue G5G8 function." (PMID 33807969, 2021).
sitosterolemia (continued). "Loss-of-function mutations in either ABCG5 or ABCG8 have been identified as a cause of sitosterolemia, a rare autosomal recessive disorder characterized by elevated plasma levels of plant sterols due to increased intestinal absorption of dietary sitosterol and decreased biliary sterol secretion." (PMID 34173968, 2021). "This inward movement is coupled with an upward movement of the conserved polar residues along the polar relay, which may be disrupted by the sitosterolemia mutation R543S in ABCG8." (PMID 32978801, 2020). "Of note, serum sitosterol levels in heterozygous ABCG5 or ABCG8 variant carriers are increased by at most 2-fold, which is modest compared to the at least 50-fold increases usually observed in patients with sitosterolemia caused by homozygous or compound heterozygous variants." (PMID 33014402, 2020). "ABCG8 mutations are found in AR sitosterolemia and AD xanthelasma." (PMID 32641076, 2020). "Mutations in human genes encoding for ABCG5 or ABCG8 have been demonstrated to cause sitosterolemia, characterized by an accumulation of sterols in blood and tissues, consequent to the enhanced intestinal absorption and decreased biliary removal of CH and plant sterols." (PMID 29420298, 2018). "Moreover, homozygous or compound heterozygous mutations in either ABCG5 or ABCG8 were observed in patients with sitosterolemia, an inborn error of metabolism." (PMID 29949603, 2018). "Mutations in ABCG5 or ABCG8 in sitosterolemic patients characterized by extremely high circulating sitosterol might explain the proatherogenic effects of sitosterolemia." (PMID 22412917, 2012). "Two mutations in either both copies of ABCG5 or both copies of ABCG8 result in sitosterolemia." (PMID 16507104, 2006). "Mutations of the ABCG5 (encodes sterolin-1) and ABCG8 (encodes sterolin-2) genes located on chromosome 2p21 cause sitosterolemia (STSL)." (PMID 37510094, 2023). "We hypothesized that hypercholesterolemic patients with a mutation in ABCG5 or ABCG8 gene exhibit better response to ezetimibe than those without, based on the fact that ezetimibe is hyper-effective for in patients with sitosterolemia caused by ABCG5 or ABCG8 genetic mutations." (PMID 31901240, 2020). "Besides, mutations in the gene ABCG5 and ABCG8 could cause sitosterolemia, which may lead to misdiagnosis of FH because of similar phenotypes." (PMID 30400955, 2018). "Previous studies have suggested that most Chinese probands with sitosterolemia have mutations in the ABCG5 gene, whereas mutations in the ABCG8 gene are more prevalent among probands of Caucasian origin." (PMID 39860331, 2025). "Among Vietnamese patients with sitosterolemia, ABCG5 gene variants were more common than ABCG8 gene variants." (PMID 39860331, 2025). "Previous studies have indicated that most Asian sitosterolemia patients, particularly Chinese or Japanese individuals, harbor the ABCG5 variant, whereas Caucasians harbor the ABCG8 variant." (PMID 39039599, 2024). "The recognized cause of sitosterolemia is homozygous or compound heterozygous mutations in the ABCG5 and ABCG8 genes leading to a loss of function of the adenosine triphosphate (ATP)-binding cassette." (PMID 39055399, 2024). "These conditions include sitosterolemia (or “phytosterolemia”), which results from biallelic rare pathogenic variants in the ATP-binding cassette transporter genes ABCG5 and/or ABCG8." (PMID 40896709, 2024). "Phytosterolemia is caused by homozygous or compound heterozygous defects in the genes ABCG5/sterolin-1 and ABCG8/sterolin-2 on chromosome 2p21." (PMID 36839186, 2023). "Sitosterolemia is a lipid disorder characterized by the accumulation of phytosterols in plasma and organs, caused by mutations in the ABCG5 and/or ABCG8 genes." (PMID 35042526, 2022). "They named their new lipid disorder β-sitosterolemia (hereon referred to as sitosterolemia), but it would be another 26 years before the discovery of ABCG5 ABCG8 as the causative gene defect." (PMID 33807969, 2021).
sitosterolemia (continued). "In humans with a rare genetic disorder known as sitosterolemia (OMIM 210250), mutations in either ABCG5 or ABCG8 genes result in loss of biliary sterol secretion and toxic accumulation of plant sterols in the body." (PMID 34117281, 2021). "Transcriptional regulation of Abcg5 Abcg8 by a small molecule LXR agonist (T0901317) precipitated its discovery as the defective gene in sitosterolemia." (PMID 33807969, 2021). "Three independent mouse models of sitosterolemia have been developed which lack functional Abcg5, Abcg8, or both half transporters." (PMID 33807969, 2021). "The ABCG5 and ABCG8 genes are co‐expressed from a common promoter located on chromosome 2p21 at the STSL (sitosterolemia) locus in a head‐to‐head orientation." (PMID 32978801, 2020). "Massively parallel sequencing results showed variants in the ABCG5 gene (NM_022436.2) for HC1 and ABCG8 gene (NM_022437.2) in HC2, both of which are known causative genes for sitosterolemia." (PMID 32845916, 2020). "ABCG5 and ABCG8, originally referred to as sterolin‐1 and‐2, were first identified in patients with the rare genetic disease sitosterolemia, a disorder of sterol absorption and secretion that elevates plant sterol levels in plasma and tissues." (PMID 32978801, 2020). "The pathogenesis of sitosterolemia is defined by pathogenic variants in either the ABCG5 and/or ABCG8 genes, which results in increased intestinal absorption and decreased biliary extraction of plant sterols." (PMID 32845916, 2020). "We believe that genetic analyses for ABCG5/ABCG8 gene are useful not only to identify carriers of sitosterolemia (patients with hyper LDL cholesterolemia), but also to select the additional therapies for further LDL reduction on top of statins." (PMID 31901240, 2020). "In sitosterolemia, pathogenic variants in the ABCG5 or ABCG8 genes result in defective ABCG5/ABCG8 efflux transporters, resulting in pathologically high absorption rates of sitosterol (15–60%)." (PMID 32845916, 2020). "In the pathogenic circumstances of sitosterolemia, variants in the ABCG5 or ABCG8 genes lead to reduced sitosterol excretion, consequently resulting in increased absorption of sitosterol." (PMID 32845916, 2020). "Cholesterol is secreted via the heterodimer transporter ABCG5/ABCG8 (genes ABCG5/ABCG8) also called sterolin, and mutations in ABCG5/ABCG8 genes can cause sitosterolemia, which has a varied clinical presentation including associated liver disease." (PMID 32432119, 2020). "Decades ago, the first report on a syndrome now known as sitosterolemia appeared, which later on was linked to mutations in the ABCG5 and ABCG8 genes leading to loss of function of the ABCG5/G8 transporter." (PMID 28383515, 2017). "In this regard, ABC transporters, such as ABCA1, ABCG5 and ABCG8, were initially found to be responsible for genetically-inherited syndromes like Tangier diseases and sitosterolemia." (PMID 28383515, 2017). "This is the case of subjects affected by sitosterolemia or mice with deletions of Abcg5/Abcg8 genes." (PMID 23951193, 2013). "Sitosterolemia is a rare autosomal recessive condition caused by mutations in two other ABC transporters: ABCG5, and ABCG8." (PMID 22649448, 2012). "In addition, we can assume that patients whose serum sitosterol level is 10 μg/mL or more are highly likely to have sitosterolemia and have deleterious ABCG5 or ABCG8 variants in both alleles." (PMID 38540356, 2024). "The ABCG5 and ABCG8 genes are located at the sitosterolemia locus on chromosome 2p21." (PMID 38509578, 2024).